RNF144B (ring finger protein 144B)
Description:
E3 ubiquitin-protein ligase which accepts ubiquitin from E2 ubiquitin-conjugating enzymes UBE2L3 and UBE2L6 in the form of a thioester and then directly transfers the ubiquitin to targeted substrates such as LCMT2, thereby promoting their degradation. Plays a crucial role in maintaining the genomic stability by controlling the degradation of multiple proteins involved in mitotic progression and DNA damage. Regulates epithelial homeostasis by mediating degradation of CDKN1A and isoform 2 of TP63. Plays a regulatory role in innate immunity by negatively regulating IRF3 activation and IFN-beta production. Mechanistically, inhibits TBK1 phosphorylation and 'Lys-63'-linked polyubiquitination independently of its E3 ligase activity. Alternatively, promotes 'Lys-27' and 'Lys-33'-linked ubiquitination of IFIH1/MDA5, promoting selective autophagic degradation of IFIH1/MDA5 to inhibit antiviral response.
Synonyms: IBRDC2; P53RFP; bA528A10.3; PIR2
Tractability: Antibody: UniProt predicts a signal peptide or a membrane-spanning region. PROTAC: UniProt records ubiquitination sites on it.
Gene: Protein-coding gene on chromosome 6 (18,387,346 to 18,468,874, forward strand). Ensembl gene ENSG00000137393.
Subcellular location: Mitochondrion membrane; Cytoplasm
Subcellular location (Human Protein Atlas): Nucleoli; Mitochondria
Pathways (Reactome):
Immune System: Antigen processing: Ubiquitination & Proteasome degradation
Gene Ontology:
Molecular function: protein binding; ubiquitin protein ligase activity; ubiquitin-protein transferase activity; ubiquitin conjugating enzyme binding; zinc ion binding
Biological process: negative regulation of apoptotic process; ubiquitin-dependent protein catabolic process; protein ubiquitination
Cellular component: cytoplasm; mitochondrial membrane; mitochondrion; cytosol; ubiquitin ligase complex
Genetic constraint (gnomAD): Loss-of-function variants: 18 observed, 26.45 expected, observed/expected ratio (o/e) 0.68, 90% interval 0.47 to 1.01. The upper end of that interval is the gene's LOEUF score, 1.01, which puts it in group 4 of 6, group 1 being the genes least tolerant of losing a copy. Missense variants: 292 observed, 319.63 expected, observed/expected ratio (o/e) 0.91, 90% interval 0.83 to 1.01. Synonymous variants: 116 observed, 119.39 expected, observed/expected ratio (o/e) 0.97, 90% interval 0.83 to 1.13.
Homologues: Orthologues: chimpanzee RNF144B (100% identical), macaque RNF144B (98% identical), guinea pig RNF144B (96% identical), dog RNF144B (95% identical), pig RNF144B (95% identical), rabbit RNF144B (95% identical), mouse Rnf144b (88% identical), rat Rnf144b (88% identical), tropical clawed frog rnf144b (72% identical), zebrafish rnf144b (60% identical), Caenorhabditis elegans C17H11.6 (27% identical), Caenorhabditis elegans Y49F6B.9 (19% identical). Paralogues in human: RNF144A (53% identical), RNF19A (27% identical), RNF19B (27% identical), ANKIB1 (23% identical), RNF217 (21% identical), ARIH1 (20% identical), ARIH2 (20% identical), RNF14 (20% identical), PRKN (17% identical).
Diseases named in the same sentence as RNF144B in open-access papers:
RNF144B is named in the same sentence as 28 diseases in open-access papers, as found by Europe PMC text mining. Sharing a sentence is not in itself a finding about the gene and the disease. The quoted sentences say what the papers report.
chordoma (6 papers, 2020 to 2025). Chordomas are rare malignant tumors arising from embryonic remnants of the notochord in axial skeleton. "WSB1, TRIM4, and RNF144b are associated with multiple cancers including neuroblastoma, chordoma and hepatocellular carcinoma." (PMID 34603387, 2021). "Its expression was reported to be up-regulated in chordoma tissues, and knockdown of RNF144B led to inhibition of cell proliferation, migration, and invasion, whose specific mechanisms are to be further explored." (PMID 40756570, 2025). "Both LINC00662 and RNF144B expressions have been shown to be aberrantly upregulated in chordoma tissues, and their knockdowns resulted in the attenuation of chordoma cell proliferation, colony formation, invasiveness, migration, EMT, and glycolysis." (PMID 34354995, 2021). "For instance, LINC00662 can facilitate chordoma development by activating RNF144B." (PMID 34721048, 2021). "RNF144B is thought to be involved in the development of chordoma through a ceRNA network." (PMID 34603387, 2021). "For example, MIR31HG could enhance proliferation, migration and invasion by up-regulating EZH2/miR-31 and then indirectly activating the oncogene RNF144B in chordoma." (PMID 32280307, 2020). "Both LINC00662 and RNF144B have been shown to be aberrantly upregulated in chordoma tissues, and the knockdown of either LINC00662 or RNF144B impeded chordoma cell proliferation, colony formation, invasiveness, migration, EMT, and glycolysis." (PMID 34354995, 2021).
endometrial cancer (4 papers, 2017 to 2025). Primary or metastatic malignant neoplasm involving the endometrium (mucous membrane that lines the endometrial cavity). "Mechanistically, RNF144B can stabilize the phosphorylation level of GSK3β downstream signaling molecules, and knockdown of the RNF144B gene in endometrial cancer cells inactivated GSK3β, leading to inhibition of cell proliferation." (PMID 40756570, 2025). "PIR2/RNF144B is a potential targeted biomarker in endometrial cancer to promote proliferation and is mainly localized on the mitochondrion membrane." (PMID 35847032, 2022). "Our results, therefore, substantiate PIR2/RNF144B as a novel candidate for targeted therapy in endometrial cancer." (PMID 29724995, 2018). "In this study, we show that the E3-ubiquitin ligase PIR2/RNF144B is a potential targetable biomarker in endometrial cancer." (PMID 29724995, 2018). "Other functions of the RNF144B gene include roles in regulation of apoptosis and cell proliferation, making the gene a possible candidate for therapeutic treatment of endometrial cancer." (PMID 28335717, 2017). "RNF144B is a potential target biomarker for endometrial cancer." (PMID 40756570, 2025). "RNF144B promotes phosphorylation of GSK3β in endometrial cancer." (PMID 40756570, 2025). "By using endometrial cancer cell lines, we demonstrated that PIR2/RNF144B is stabilised via phosphorylation downstream of GSK3β and this is necessary for the proliferation of endometrial cancer cells, in the absence of oestrogenic growth stimuli." (PMID 29724995, 2018).
bovine tuberculosis (2 papers, 2021 to 2025). "RNF144B has been strongly associated with susceptibility to bovine tuberculosis, and genome-wide association analysis revealed that RNF144B is the gene most associated with single nucleotide polymorphisms on bovine autosomes." (PMID 40756570, 2025). "The role of RNF144B toward bovine tuberculosis susceptibility was also reported in Holstein–Friesian cattle." (PMID 34306039, 2021).
gastric cancer (2 papers, 2024 to 2025). A primary or metastatic malignant neoplasm involving the stomach. "Notably, miR-100 overexpression in gastric cancer specimens establishes an oncogenic signaling axis through direct transcriptional activation of RNF144B." (PMID 40756570, 2025).
lung adenocarcinoma (2 papers, 2024 to 2025). A carcinoma that arises from the lung and is characterized by the presence of malignant glandular epithelial cells. "RNF144B deficiency leads to chromosomal instability and increased aneuploidy in human lung adenocarcinomas." (PMID 38685100, 2024). "Importantly, RNF144B deficiency in lung adenocarcinoma cells induces their resistance to DNA damage, CIN or cell cycle based anti-cancer therapies." (PMID 38685100, 2024). "Furthermore, RNF144B-deficient lung adenocarcinoma cells exhibited resistance to cell cycle inhibitors that induce chromosomal instability." (PMID 38685100, 2024). "Together, insights from human cancer analyses suggest potential tumor suppressor role of RNF144B in lung adenocarcinoma." (PMID 38685100, 2024). "Our research underscores RNF144B's pivotal role as a tumor suppressor, particularly in lung adenocarcinoma." (PMID 38685100, 2024). "Given that human cancer data indicated the importance of RNF144B in tumor suppression in lung context, we sought to interrogate the role of RNF144B using lung adenocarcinoma models." (PMID 38685100, 2024). "In conclusion, our study establishes RNF144B as a critical tumor suppressor, with particular significance in lung adenocarcinomas." (PMID 38685100, 2024). "To evaluate whether RNF144B plays a role in lung adenocarcinoma growth we knockout RNF144B in non-transformed KRASG12D expressing lung bronchial 3KT epithelial cell line by CRISPR/Cas9 (sgRNF144B3KT)." (PMID 38685100, 2024).
lymphoma (2 papers, 2024 to 2025). A malignant (clonal) proliferation of B- lymphocytes or T- lymphocytes which involves the lymph nodes, bone marrow and/or extranodal sites.
ovarian carcinoma (2 papers, 2024 to 2025). A malignant neoplasm originating from the surface ovarian epithelium. "RNF144B plays an important role in the oncogenesis and metastatic dissemination of ovarian cancer, and the level of RNF144B is significantly higher in ovarian cancer tissues than in normal ovarian and benign ovarian tumor tissues." (PMID 40756570, 2025). "PKM2, MRPS12, NDUFC2, HPDL, MRPL14, COA6 and RNF144B were significantly upregulated in ovarian cancer tissues than in normal tissues (P < 0.05), while RPL23, FGFR1OP2, CAPN10, ALDH1L1 and ACSM1 were significantly down-regulated (P < 0.05)." (PMID 39478854, 2024). "PKM2, MRPS12, NDUFC2, HPDL, MRPL14, COA6 and RNF144B were significantly upregulated in ovarian cancer, but the down-regulation of NDUFC2, HPDL, MRPL14, COA6 and RNF144B was associated with poor prognosis in patients with ovarian cancer." (PMID 39478854, 2024).
B cell lymphoma (1 paper, 2024). "RNF144B has been described as a potent tumour suppressor in mouse B cell lymphoma models." (PMID 38685100, 2024).
glioblastoma (1 paper, 2024). The most malignant astrocytic tumor (WHO grade IV).
leukemia (1 paper, 2025). A malignant (clonal) hematologic disorder, involving hematopoietic stem cells and characterized by the presence of primitive or atypical myeloid or lymphoid cells in the bone marrow and the blood. "RNF144B promotes ubiquitination degradation of NPM, which promotes leukemia." (PMID 40756570, 2025).
lung carcinoma (1 paper, 2024). "Our results provide preclinical evidence that dysregulation of DNA repair and mitotic fidelity caused by RNF144B deficiency enables lung cancer cells to evade the cytotoxic effects of drugs that cause CIN, DNA damage (through topoisomerase II inhibition) or mitotic alterations." (PMID 38685100, 2024). "Our studies coupled with in vivo, 3D or 2D cellular models’ analysis and clinical data, demonstrate that RNF144B suppresses cell proliferation and transformation, in particular in the context of lung cancer." (PMID 38685100, 2024).
Obesity (1 paper, 2022). Accumulation of substantial excess body fat. "Among them, the upregulated gene BCL2A1 is common in CVD, HTN, obesity, and aging; RNF144B and PTGIS are common in HCL, obesity, aging, and CVD; G0S2, CXCL1, ACKR3, and PTPRD are found in HTN, aging, and CVD; TGFB2, CA12, and MSR1 are familiar in obesity, aging, and CVD." (PMID 36035865, 2022).
psoriasis (1 paper, 2025). An autoimmune condition characterized by red, well-delineated plaques with silvery scales that are usually on the extensor surfaces and scalp. "The microarray determination of miR-31 expression and quantitative detection of the miR-31 target gene expression showed that the expression of RNF144B in the psoriasis group was higher than that of the control group." (PMID 40756570, 2025). "It was further revealed that RNF144B promotes T-lymphocyte activation by inhibiting the proliferation of dermal mesenchymal stem cells (DMSCs) and thereby participates in the pathogenesis of psoriasis." (PMID 40756570, 2025).
Sepsis (1 paper, 2025). Sepsis is defined as life-threatening organ dysfunction caused by a dysregulated host response to infection. "Knockdown of RNF144B in BMDM cells resulted in increased release of inflammatory factors, suggesting that RNF144B can attenuate the inflammatory response caused by sepsis." (PMID 40756570, 2025). "The expression level of RNF144B was significantly elevated in the peripheral blood mononuclear cells from patients with sepsis, as well as after induction of bone marrow stromal stem cells by LPS." (PMID 40756570, 2025).
viral infection (1 paper, 2024). "In addition, the p-TBK1 level was increased in Rnf144b KO cells following viral infection." (PMID 39285245, 2024).
tumor (7 papers, 2018 to 2025). "GFP-labeled shRNF144BMEF and shTRP53MEF dominated the resulting subcutaneous tumours, validating the in vivo growth advantage caused by RNF144B knockdown." (PMID 38685100, 2024). "In this work, we investigate RNF144B's impact on tumor suppression beyond the hematopoietic compartment in human cancers." (PMID 38685100, 2024). "Analysis of these cells demonstrated that attenuated expression of RNF144B protein increased tumour growth in vivo upon subcutaneous injection into immunocompromised mice." (PMID 38685100, 2024). "Supported by clinical data, our study suggests that RNF144B plays a pivotal role in maintaining genomic stability during tumor suppression." (PMID 38685100, 2024). "The precise molecular mechanism and target genes involved in RNF144B-mediated maintenance of genomic stability and tumor prevention are yet to be determined." (PMID 38685100, 2024). "We focused on better understanding RNF144B, which has been a poorly characterized tumor suppressor identified as one of the most significant hits in the screen." (PMID 38685100, 2024). "We found that RNF144B expression was both downregulated or upregulated in different tumour tissues when compared to normal tissues, respectively, indicating its context-dependent regulation." (PMID 38685100, 2024). "In contrast, RNF144B up-regulation correlated with tumor cell resistance against docetaxel and asparaginase." (PMID 36497225, 2022). "RNF144B acts as an oncogenic protein in tumor development and plays a crucial role in cell proliferation, which might affect platelet generation by promoting the proliferation of bone marrow megakaryocytes." (PMID 39331630, 2025). "To test if RNF144B could have a tumour suppressor activity in human cancers, we analyzed its expression in publicly available datasets of cancer and healthy tissues (XenaBrowser)." (PMID 38685100, 2024). "All together, we found that RNF144B is a tumour suppressor involved in maintaining genomic stability and its knockdown triggers the appearance of several mitotic defects that eventually lead to chromosomal aberrations and DNA damage in oncogene expressing cells." (PMID 38685100, 2024). "Importantly RNF144B role as a tumour suppressor in other cellular and oncogene driven contexts is still unknown." (PMID 38685100, 2024). "The expression of CCL20, CD70, PCDH7, DCBLD2, and MMP14 genes were remarkably more elevated within LUAD samples than adjacent non-tumorous tissues, where PIK3R5, RNF144B, BTG2, CD69, and MEP1A genes were the opposite." (PMID 36497225, 2022).
tumor (continued). "The tumor suppression and mechanism are as follows: RNF144B promotes the proliferation of tumor cells and also promotes the stabilization of tumor chromosomes, which leads to the suppression of LUAD by RNF144B." (PMID 40756570, 2025).